APOA1 (apolipoprotein A1)
Diseases named in the same sentence as APOA1 in open-access papers (continued):
Sharing a sentence is not in itself a finding about the gene and the disease.
Hypertension (continued). "A nomogram was developed to predict cognitive impairment, incorporating hypertension, CSVD burden, apolipoprotein A1 (ApoA1) levels, and age." (PMID 38952470, 2024). "Meanwhile, groups with higher HDL-c and APOA1 have remarkably lower BMI, TG, UA, and HOMA-IR levels and a lower prevalence of hypertension (p < 0.05)." (PMID 37396919, 2023). "Furthermore, CVD risk in hypertension patients is more closely associated with the levels of apolipoprotein, which plays a crucial role in the protective functions of HDL, than with the quantitative levels of HDL-C, whereby CVD patients have low concentrations of serum apolipoprotein A1 (ApoA1)." (PMID 32824020, 2020). "The levels of FPG, TC, LDL-C, and the percentages of T2D and hypertension were higher but the concentrations HDL-C, ApoA1 and the ApoA1 to ApoB ratio were lower in persons who suffered from CHD than in controls (P < 0.05)." (PMID 29439709, 2018). "Strong positive associations were seen for all alcohol variables in both studies with hypertension, raised HDL, ApoA1 and BNP, for all men and also among drinkers." (PMID 23645505, 2013). "Our research indicated that even when accounting for factors such as AF, Hypertension, SBP, Stroke, Type 2 diabetes, Triglycerides, LDL, HDL, apolipoprotein A1 levels, apolipoprotein B levels, and apolipoprotein E levels, migraine continues to elevate the risk of AD." (PMID 38903170, 2024). "After adjustment for age, BMI, diabetic duration, menopausal duration, hypertension, sedentary behavior, smoking, drinking (Model 1), HbA1c, TG, HDL-c, APOA1, LDL-c, creatinine, ALT, UA, and HOMA-IR (Model 2), APOA1 was shown to be positively correlated with OC, L1-L4 BMD, and T-score." (PMID 37396919, 2023). "ApoA1 level was lower but apoB level was higher in women with hypertension than those without hypertension after 8 years." (PMID 36551995, 2022). "Compared with females, males had significantly higher age, BMI, SBP, DBP, ALT, AST, ZJU index, Cr, urea, UA, LDL-C, non-HDL-C, TG, ApoB, glucose, HbA1c, and prevalence of hyperglycemia and hypertension, whereas lower eGFR, HDL-C, and ApoA1 levels (all p < 0.001)." (PMID 35770226, 2022). "Mean height, SBP, DBP, pulse pressure, TG, the percentages of subjects who consumed alcohol or smoked cigarettes, and the prevalence of hypertension were higher (p ≤ 0.003), whereas mean HDL-C, ApoA1, and the ratio of ApoA1 to ApoB were lower (p ≤ 0.001) in IS than in control groups." (PMID 35559044, 2022). "A case-control study indicated that there was a rise in serum apoB100 and apoB100:apoA1 ratio in the patients with essential hypertension, which was not seen in the matched control counterparts." (PMID 36551995, 2022). "Age, sex, insulin resistance, systemic hypertension, TG, ALT, AST, GGT, AST/ALT ratio, α2-macroglobulin, haptoglobin, apolipoprotein A1, total bilirubin, fasting blood glucose and fibrosis-4 were found to be associated with NASH and have been used in various diagnostic panels." (PMID 27248665, 2016). "Among women, the association of marital status with risk of AMI was consistently observed in women with a high or low education level, in those with a high or low income, in those with or without history of hypertension, and in those with a high or low ApoB/ApoA1 ratio." (PMID 22245707, 2012). "Their final model included fewer years of education, a shorter history of hypertension, higher MDS-UPDRS motor scores, elevated levels of TG and ApoA1, and noncarrier status of the SNCA rs6826785 genetic marker." (PMID 39767666, 2024). "However, there were no statistical differences neither in percentage of hypertension, DM, smoking, drinking, nor in levels of BMI, hemoglobin, ALT, AST, BUN, Cr, UA, FBG, TG, HDL-C, ApoA1 or TyG index between the two groups (p-values >0.05)." (PMID 40027894, 2025).
Hypertension (continued). "Sex (1 = male, 2 = female), diabetic family history (1 = yes, 0 = no), smoking (1 = smoker, 0 = nonsmoker), hypertension (1 = hypertension, 0 = nonhypertension), BMI, disease duration, HbA1c, 25(OH)D, TC, HDL, TG, LDL, ApoB, ApoA1, and LPA were regarded as covariates." (PMID 33299499, 2020).
coronary artery disease (156 papers, 2007 to 2026). "Plasma concentration of high-density lipoprotein cholesterol (HDL-C) is among the most important risk factors for coronary artery disease and apolipoprotein A1 (APOA1) is an essential apolipoprotein that constitutes HDL." (PMID 42055329, 2026). "Elevated ApoA1 levels are associated with decreased risk of coronary diseases, while high ApoB levels and high ApoB/ApoA1 ratios were related to increased cardiovascular events." (PMID 41601590, 2026). "Based on another study conducted in China, the ApoB:ApoA1 ratio was a more effective predictor of coronary heart disease risk in overweight and obese individuals than traditional lipid measures like LDL-C." (PMID 40944180, 2025). "ApoA1 levels below ~75 mg/dL in men or ~80 mg/dL in women are considered low and possibly associated with higher risk of coronary artery disease." (PMID 40944180, 2025). "The ratio of ApoB to apoA1 (ApoB/apoA1) is frequently used as a marker to assess the risk of coronary heart disease associated with lipoproteins." (PMID 40678973, 2025). "Concentrations of Chol, TG, ApoB, and ApoA1, are associated with coronary heart disease and carotid plaques." (PMID 38895187, 2024). "In conclusion, we found that prothrombotic gene variants and APOA1 rs5069 polymorphism were statistically significantly associated with coronary artery disease." (PMID 39295604, 2024). "In our study, we found that prothrombotic gene variants and APOA1 rs5069 polymorphism were statistically significantly associated with coronary artery disease." (PMID 39295604, 2024). "Increased levels of ApoA-1 are more strongly associated with a lower risk of coronary artery disease, compared with increased levels of HDL-C." (PMID 37165443, 2023). "For example, the association between high ApoA1 levels and premature coronary heart disease is well known." (PMID 37420190, 2023). "Data from Indian patients with acute myocardial infarction (AMI) demonstrated that the ApoB/ApoA1 ratio was a better discriminator of coronary artery disease (CAD) risk than other conventional lipid ratios including the ratio of TC/HDL-C and LDL/HDL-C." (PMID 34996506, 2022). "Lower HDL-C/apoA1 was still associated with a higher occurrence of coronary heart disease, but the original association between lower HDL-C/apoA1 and more severe coronary artery stenosis was lost in patients with renal insufficiency." (PMID 34772349, 2021). "According to epidemiological research, the ratio of APOA1 to APOB was a good predictor of coronary heart disease risk." (PMID 34702323, 2021). "ApoB/apoA1 can be used as a predictor of coronary heart disease risk, but its effect on prognosis of ACS patients is rarely reported." (PMID 32539722, 2020). "The “Diseases and Disorders” analysis in the IPA showed that APOA1 was associated with disorder of lipid metabolism, coronary disease, acute coronary syndrome, and occlusion of blood vessels." (PMID 32566106, 2020). "The APOB/APOA1 ratio, an effective predictor of coronary heart disease risk significantly decreased by about 8% after resistance training." (PMID 31195651, 2019). "This region of the ZNF259/BUD13, APOA1/C3/A4/A5 genes has also been associated with coronary artery disease." (PMID 25688259, 2015). "The individuals with the APOA1 -75 A allele were likely to have a lower risk of coronary artery disease as a result of its effect on higher serum concentrations of ApoA1 and HDL-C." (PMID 26537097, 2015). "Many evidences were reported showing that apolipoprotein A1/C3/A4/A5 gene cluster is associated with premature coronary artery disease and serum lipid levels." (PMID 24684850, 2014). "A study found the APOA1 -75 G/A polymorphism was significantly associated with plasma triglyceride levels in men with coronary artery disease from the REGRESS study." (PMID 24209603, 2013). "A number of clinical studies demonstrate the association between low ApoA1 levels and an increased risk of MI and coronary artery disease." (PMID 21692678, 2011).
coronary artery disease (continued). "APOA1 relates to lower observational risk of coronary artery disease." (PMID 40371638, 2025). "Initially discovered in 1998 by Dinu and colleagues in patients with SLE, anti-apoA-1 IgG were found to be associated with a higher prevalence and incidence of coronary artery disease (CAD), independently of traditional CV risk factors in autoimmune and non-autoimmune settings." (PMID 33110193, 2020). "Polymorphisms of APOA1 are associated with coronary artery disease and it is an interactor of the APOE, a well‐described genetic risk factor for Alzheimer's and cardiovascular diseases and the locus with the largest statistical support for an association with extreme longevity." (PMID 28295945, 2017). "Therefore, the ferulic acid intake could decrease the coronary heart disease risk associated with overweight and obesity via the reduction of the ApoB/ApoA1 ratio and LDL-C." (PMID 28661434, 2017). "A study from China involving 826 patients with coronary heart disease showed that ApoB/ApoA1 was still significantly correlated with the adjusted Gensini score." (PMID 40775270, 2025). "For this reason, it is noteworthy that overtly hypothyroid patients are at increased risk for coronary heart disease despite having elevated HDL-C and apoA-1 levels." (PMID 38379854, 2024). "CAD: coronary artery disease; ApoA1: apo lipoprotein A1; HDL-C: high-density lipoprotein cholesterol." (PMID 38914982, 2024). "Due to the high number of identified loci, overlap with other diseases was high and included apolipoprotein A1, coeliac disease, coronary artery disease, vasculitis, and cholangitis (in addition to the diseases associated with the other clusters)." (PMID 39168988, 2024). "ApoA1 was previously identified as a better predictor for ischemic heart disease and cardiovascular mortality than HDL, low-density lipoprotein, or apolipoprotein B." (PMID 36197585, 2023). "Variants in the GPR149 gene, which encodes a seven-transmembrane G protein-coupled receptor (GPCR) class A family member, have been associated with coronary artery disease, HDL cholesterol level, and apolipoprotein A1 level." (PMID 35869121, 2022). "The apoB/apoA1 ratio also showed improved accuracy over TC/HDL-C in predicting adverse cardiovascular events in a prospective study of patients with established coronary heart disease (CHD)." (PMID 34677405, 2021). "When comparing the accuracy of the prediction of coronary heart disease mortality based on apolipoprotein levels, they found that both apoB and the apoB/apoA1 ratio proved better than traditional cholesterol markers." (PMID 34677405, 2021). "With the presence of renal insufficiency, HDL-C/apoA1 was higher in patients with coronary heart disease." (PMID 34772349, 2021). "It follows that apoB/apoA1 is positively correlated with the severity of coronary artery diseases and the prediction of long-term prognosis." (PMID 32539722, 2020). "The role of HDL in improving coronary artery disease is closely related to its main structural component ApoA1." (PMID 32103113, 2020). "ApoA1 is a component of high density lipoprotein (HDL), which is associated with reduced risk of coronary heart disease." (PMID 26637205, 2015). "This strategy is motivated by the fact that plasma levels of HDL-cholesterol and ApoA1 in humans correlate inversely and independently with coronary heart disease." (PMID 24586211, 2014). "Because ApoA1 is the major protein component of HDL, low plasma ApoA1 levels have been associated with increased risk of coronary artery disease." (PMID 24093822, 2013). "In large meta-analyses, associations between FADS1-2-3 and carotid intima media thickness, AGPAT1 and type 2 diabetes, and APOA1 and coronary artery disease were observed." (PMID 22359512, 2012). "We investigated the relationship of apoB/apoA1 ratio and coronary heart disease (CHD) in persons who were overweight or obese." (PMID 23554700, 2011).
coronary artery disease (continued). "Accumulating evidence suggests that lipoprotein ratios may outperform individual lipid parameters as predictors of coronary heart disease, with the ApoB100/ApoA1 ratio identified as an optimal predictor of CHD." (PMID 38393015, 2024). "ApoB is present in LDL-C, whereas APOA1 is present in HDL-C; it has been suggested that an increase in Apo B concentrations and a decrease in Apo A1 concentrations are positively correlated with ischemic heart disease risk." (PMID 39683045, 2024). "The coronary heart disease rate, atrial fibrillation rate, degree of carotid stenosis, white blood cell count, neutrophil percentage, apolipoprotein A1, NHR, NLR, and C-reactive protein (CRP) were higher in the moderate-to-severe stroke group than in the mild stroke group." (PMID 37327299, 2023). "Increased oxTrp72-apoA1 levels were correlated with an increased coronary artery disease risk and cardiovascular risk, even after adjusting for traditional CVD risk factors, i.e., apoA1, MPO, and high sensitivity C-reactive protein levels, and lipid lowering medication use." (PMID 36362423, 2022). "Some clinical studies indicate ApoA1 may be a better prognostic marker than LDL-C or HDL-C in prediction of severity of coronary artery disease; its link with monocyte recruitment may factor into this." (PMID 33717107, 2021). "Therefore, we believed the effects of lipids and lipoprotein on the normal weight and overweight groups were different, and apoB/apoA1 on the incidence of coronary heart disease among overweight subjects was a more meaningful prediction." (PMID 23554700, 2011). "In the present study, along with elevated LDL-cholesterol, several blood lipid profiles, including non-HDL-c, apoB, Lp(a), TC/HDL-c and apoB/apoA1 ratio, were significantly increased and were associated with the severity of coronary artery disease in FH patients." (PMID 38443803, 2024). "Furthermore, HDL levels are inversely correlated with percutaneous coronary intervention-related myocardial infarction risks and ApoA1 plasma levels correlate positively with improved outcomes in coronary artery bypass graft surgery patients, suggesting a protective role in ischemic heart disease." (PMID 30233357, 2018). "In terms of CMD, a noteworthy correlation was observed between the increase in the ApoB/ApoA1 ratio and various CMD, including ischemic heart disease, major adverse cardiovascular events, aortic aneurysm, cerebral ischemic disease and so on (all PFDR<0.05)." (PMID 38310324, 2024). "This study investigated the possible relationship between the Apo lipoprotein A1 /high-density lipoprotein cholesterol (ApoA1/HDL-C) ratio and coronary artery disease (CAD) in patients with type 2 diabetes (T2D)." (PMID 38914982, 2024). "The HDL apolipoproteomic score (pCAD) calculated using this method was associated with the presence of coronary artery disease (CAD), independent of circulating apoA-1 and other conventional cardiovascular risk factors." (PMID 37958510, 2023). "Administration of MDCO-216 (ApoA-1 Milano/POPC) promoted ABCA1-mediated cholesterol efflux and pre-β HDLs in healthy volunteers and patients with stable coronary artery disease." (PMID 31979310, 2020). "The lower the expression of miR-92a and miR-106b in patients with coronary artery disease, the lower the levels of HDL-C and ApoA-1 in vivo, and these miRNAs may play an independent role." (PMID 34781979, 2021). "Compared with the unlikely FH patients with ACS, the FH patients had higher levels of TC, LDL-c, apoB, Lp(a), non-HDL-c, TC/HDL-c and apoB/apoA1 ratio, more severe coronary artery diseases and greater prevalence of left main and triple or multiple vessel lesions." (PMID 38443803, 2024).
coronary artery disease (continued). "Compared with the unlikely FH patients, FH patients with ACS had higher levels of TC, LDL-c, apoB, Lp(a), non-HDL-c, TC/HDL-c and apoB/apoA1 ratio and had more serious coronary diseases and greater prevalence of left main, triple-, or multiple-vessel lesions at the time of discharge." (PMID 38443803, 2024). "Previously, we showed that higher apoA1 in HDL that contained apoC3 is associated with a higher risk of type 2 diabetes and coronary heart disease, whereas higher apoA1 in HDL that lacked apoC3 was associated with a lower risk of type 2 diabetes and coronary heart disease." (PMID 33142714, 2020). "Based upon these previous findings on diabetes and coronary heart disease risk, two conditions strongly linked to NAFLD, we examined the association of apoA1 in HDL that contained or lacked apoC3 with liver fat content and NAFLD in the Multi-Ethnic Study of Atherosclerosis (MESA)." (PMID 33142714, 2020). "APOA1 deficiency, a codominant disorder, is characterized by almost absence of HDL-c and apolipoprotein A-I (APOA-I), as well as premature coronary heart disease." (PMID 37138899, 2022). "First, we could not compare plasma levels of ApoC-2, ApoA-1, 14–3–3 protein ζ/δ, and ITIH4 in patients with TAK with those in patients with other inflammatory diseases, such as systemic lupus erythematosus, rheumatoid arthritis, coronary artery diseases, and other bacterial infectious diseases." (PMID 34556808, 2021).